TMEM233 (transmembrane protein 233)
Description:
Probable accessory protein of voltage-gated sodium channels.
Synonyms: DSPB2; IFITMD2
Tractability: Antibody: UniProt places it where antibodies can reach, with high confidence; its Gene Ontology location is reachable by antibodies, with high confidence; UniProt predicts a signal peptide or a membrane-spanning region. PROTAC: ubiquitination databases record sites on it.
Gene: Protein-coding gene on chromosome 12 (119,593,774 to 119,643,075, forward strand). Ensembl gene ENSG00000224982.
Subcellular location: Cell membrane
Subcellular location (Human Protein Atlas): Nucleoplasm
Gene Ontology:
Molecular function: protein binding
Cellular component: plasma membrane; membrane
Genetic constraint (gnomAD): Loss-of-function variants: 5 observed, 10.17 expected, observed/expected ratio (o/e) 0.49, 90% interval 0.26 to 1.03. The upper end of that interval is the gene's LOEUF score, 1.03, which puts it in group 4 of 6, group 1 being the genes least tolerant of losing a copy. Missense variants: 121 observed, 143.06 expected, observed/expected ratio (o/e) 0.85, 90% interval 0.73 to 0.98. Synonymous variants: 56 observed, 55.37 expected, observed/expected ratio (o/e) 1.01, 90% interval 0.81 to 1.26.
Homologues: Orthologues: chimpanzee TMEM233 (100% identical), macaque TMEM233 (99% identical), dog TMEM233 (92% identical), rabbit TMEM233 (92% identical), pig TMEM233 (91% identical), guinea pig TMEM233 (86% identical), mouse Tmem233 (86% identical), rat Tmem233 (83% identical), tropical clawed frog tmem233 (66% identical), zebrafish TMEM233 (51% identical). Paralogues in human: TRARG1 (38% identical), PRRT2 (36% identical), PRRT1B (21% identical), PRRT1 (18% identical).
Diseases named in the same sentence as TMEM233 in open-access papers:
TMEM233 is named in the same sentence as 7 diseases in open-access papers, as found by Europe PMC text mining. Sharing a sentence is not in itself a finding about the gene and the disease. The quoted sentences say what the papers report.
breast carcinoma (1 paper, 2021). "For the key specific DEGs in Normal-like subtype, the prognostic analysis of IDH1-AS1 and TMEM233 was performed using data from TCGA database, which was not meaningful due to the small number of breast cancer samples from this subtype in TCGA database." (PMID 33644115, 2021).
neuroblastoma (1 paper, 2026). Neuroblastoma (NB) is the most common solid, extracranial childhood tumor. "To address this possibility, we performed patch clamp and calcium imaging experiments on mouse DRG neurons and on neuroblastoma ND7/23 and CHO cells expressing Nav1.8 and TMEM233." (PMID 41854608, 2026).
TMEM233 also shares sentences with these, for which no sentence is quoted: benign familial infantile epilepsy (1 paper); brain cancer (1); neurological diseases (1); paroxysmal dyskinesia (1); tumor (1).